USP17L3 (ubiquitin specific peptidase 17 like family member 3)
Description:
Deubiquitinating enzyme that removes conjugated ubiquitin from specific proteins to regulate different cellular processes that may include cell proliferation, progression through the cell cycle, apoptosis, cell migration, and the cellular response to viral infection.
Synonyms: USP17B; USP17F
Tractability: No criterion of Open Targets' tractability assessment is met for any kind of drug.
Gene: Protein-coding gene on chromosome 8 (7,976,393 to 7,977,985, reverse strand). Ensembl gene ENSG00000225327.
Subcellular location: Nucleus; Endoplasmic reticulum
Pathways (Reactome):
Metabolism of proteins: Ub-specific processing proteases
Gene Ontology:
Molecular function: cysteine-type deubiquitinase activity
Biological process: regulation of apoptotic process; protein deubiquitination
Cellular component: endoplasmic reticulum; nucleus
Homologues: Paralogues in human: USP17L1 (99% identical), USP17L4 (97% identical), USP17L2 (97% identical), USP17L8 (95% identical), USP17L18 (95% identical), USP17L11 (94% identical), USP17L17 (94% identical), USP17L20 (94% identical), USP17L22 (94% identical), USP17L19 (94% identical), USP17L24 (94% identical), USP17L25 (94% identical), and 59 more.